PHLDA1 (pleckstrin homology like domain family A member 1)
Diseases named in the same sentence as PHLDA1 in open-access papers (continued):
Sharing a sentence is not in itself a finding about the gene and the disease.
glioma (11 papers, 2015 to 2025). A benign or malignant brain and spinal cord tumor that arises from glial cells (astrocytes, oligodendrocytes, ependymal cells). "Data from the GEPIA2 (gene expression profiling interactive analysis) server show that PHLDA1 is significantly upregulated in several malignancies, including pancreatic cancer, lower‐grade glioma, and melanoma, and it is significantly associated with poor prognosis in pancreatic cancer." (PMID 35570408, 2022). "PHLDA1 is known to promote glioma progression, whereas miR-194 suppresses the proliferation and migration of glioma by regulating PHLDA1." (PMID 39630301, 2025). "SNHG1 regulates pleckstrin homology like domain family A member 1 (PHLDA1) expression by sponging miR-194, leading to an increased glioma cell glucose uptake, proliferation, migration, invasion, angiogenesis and in vivo tumor growth." (PMID 33652661, 2021). "SNHG1 competitively binds to miR-194 to relieve the inhibitory effect of miR-194 on PHLDA1 expression, thus promoting glioma progression." (PMID 32536864, 2020). "In vitro and in vivo assays suggested that SNHG1 promoted glioma progression by functioning as a sponge for miR-194 and then inducing the high expression of pleckstrin homology like domain family A, member 1 (PHLDA1)." (PMID 32802843, 2020). "In the current study, we showed that PHLDA1 is upregulated in glioma and promotes the malignant progress of glioma." (PMID 31189920, 2019). "We detected the expression of PHLDA1 in glioma cell lines as well and the result is consistent with data from the glioma tissues." (PMID 31189920, 2019). "Overall, these results suggest that SNHG1 promotes glioma progression by sponging miR-194 and regulating PHLDA1 expression." (PMID 31189920, 2019). "The present study suggests that SNHG1 acts as a sponge for miR-194 and that miR-194 targets PHLDA1 to regulate glioma progression." (PMID 31189920, 2019). "PHLDA1 mRNA was also verified as a direct target of miR-194 in glioma." (PMID 39630301, 2025). "Three of these glioma-associated SNPs were pleiotropic: RTEL1 (rs1291209: allergic disease asthma hay fever or eczema), CDKN2B (rs6475604: coronary heart disease, glaucoma, vertical cup disc ratio), and PHLDA1 (rs1565765: atrial fibrillation)." (PMID 33495464, 2021). "Taken together, our study shows that SNHG1 promotes glioma progression by competitively binding to miR-194 to regulate PHLDA1 expression, which may provide a novel therapeutic strategy for glioma." (PMID 31189920, 2019). "Functional assays revealed that SNHG1 promotes glioma progression via miR-194 to regulate PHLDA1." (PMID 31189920, 2019). "Taken together, these results suggest that PHLDA1 promotes the progression of glioma in vivo." (PMID 31189920, 2019). "In conclusion, our study reports, for the first time, that SNHG1/miR-194/PHLDA1 signalling is involved in the progression of glioma, which leads to a more malignant phenotype and may be a novel potential therapeutic target for glioma." (PMID 31189920, 2019). "PHLDA1 is overexpressed in glioma and correlates with the grade of glioma." (PMID 31189920, 2019). "Thus, we conclude that miR-194 inhibits glioma progression by targeting PHLDA1." (PMID 31189920, 2019). "Hence, the SNHG1/miR-194/PHLDA1 signalling pathway may be a potential therapeutic target for glioma." (PMID 31189920, 2019). "PHLDA1 expression is increased in patient-derived gliomas and correlated with increased expression of a long non-coding RNA proposed to hybridize with microRNA, miR-194, responsible for silencing PHLDA1 expression." (PMID 32429563, 2020). "To elucidate the ceRNA mechanism of SNHG1 in glioma, we conducted a series of experiments to explore whether SNHG1 regulates the expression of PHLDA1 in a miR-194-dependent manner." (PMID 31189920, 2019). "Collectively POLR3B, ETFA, VTI1A, ZBTB16 and PHLDA1 are altered in 8% (22/286) of LGG as compared with 3% (8/273) of GBM (P=0.014) providing support for these genes having a role in glioma tumorigenesis." (PMID 26424050, 2015).
glioma (continued). "Moreover, further analysis revealed that SNHG1 regulates pleckstrin homology like domain family A, member 1 (PHLDA1) expression via the sponging miR-194, leading to the subsequent promotion of glioma cell glucose uptake, proliferation, migration, invasion, angiogenesis and in vivo tumour growth." (PMID 31189920, 2019).
melanoma (9 papers, 2008 to 2025). A malignant, usually aggressive tumor composed of atypical, neoplastic melanocytes. "PHLDA1 has been reported to induce apoptosis in various cells including T cells, endothelial cells and melanoma cells." (PMID 35928827, 2022). "The PHLDA1 gene is of interest as it has been suggested to be a tumor suppressor in breast adenocarcinoma and melanoma." (PMID 18597688, 2008). "In addition, according to Oncomine-based expression analysis, PHLDA1 was found to be upregulated in brain, colorectal, kidney, lymphoma, melanoma, myeloma, ovarian, and pancreatic cancer but downregulated in breast, esophageal, cervical, liver cancer, head and neck, and lymphoma cancer." (PMID 38921000, 2024).
colon cancer (7 papers, 2010 to 2025). "For example, colon cancer has been associated with PHLDA1 overexpression, and PHLDA1 knockdown prevents anchorage-independent cell growth and reduces cell migration in colon cancer cells." (PMID 38921000, 2024). "Furthermore, PHLDA1/2 were upregulated in association with the presence of ERK-activating oncogenes in colon cancers." (PMID 35831322, 2022). "PHLDA1 is a potential epithelial stem cell marker that promotes colon cancer cell motility and proliferation in the small and large intestines of humans." (PMID 38921000, 2024). "An example of gained enhancers is shown for PHLDA1, a gene upregulated in colon cancer and involved in tumor cell proliferation and migration." (PMID 33879786, 2021). "Finally, the pleckstrin homology‐like domain in family A (PHLDA1) has implications for intestinal tumorigenesis, as demonstrated by siRNA‐mediated suppression of PHLDA1 in colon cancer cells." (PMID 40013338, 2025). "Indeed, immunohistochemical analyses of clinical tumor samples demonstrated that PHLDA1/2 proteins were highly expressed in lung, pancreas, and colon cancers." (PMID 35831322, 2022). "It has also been suggested that PHLDA1 is a putative epithelial stem cell marker in the small and large human intestine and contributes to the migration and proliferation of colon cancer cells, and it may contribute to the understanding of the oncogenic mechanism of colorectal carcinogenesis." (PMID 33982211, 2021). "Pleckstrin homology like domain family A member 1 (PHLDA1) plays a crucial role in promoting the migration and proliferation of colon cancer cells by regulating the expression level of ITGA2 in colonic malignant tumors." (PMID 37881431, 2023). "A significant overlap was detected with several relevant gene families, including colon cancer progression (e.g., FN1, IGBP3, PLAUR and TIMP1; P=0.00052), tumour cell apoptosis (e.g., BID, TNFRSF21, PHLDA1 and NOTCH1; P=1.46 × 10–6) and cell proliferation (e.g., CTGF, SPP1, FOLR1 and SPARC)." (PMID 21119668, 2010).
colorectal cancer (7 papers, 2020 to 2025). A primary or metastatic malignant neoplasm that affects the colon or rectum. "Another contrasting function of PHLDA1 emerged in HCT116, HT29, and SW48 colorectal cancer cells, where PHLDA1 upregulation was associated with resistance to cetuximab, a monoclonal antibody targeting EGFR." (PMID 39630301, 2025). "We also noted that PHLDA1 mutations covered the pleckstrin domain, with a hotspot in F252Tfs*5/Y251Tfs*5, which were primarily seen in colorectal cancer and bladder cancer." (PMID 38921000, 2024). "The 500 kbp region downstream of PHLDA1 encompassed 41 enhancer regions in HCT 116 colorectal cancer cells of which 35 overlapped with four super‐enhancers." (PMID 33502116, 2021). "On the contrary, the migration ability of colorectal cancer cells with PHLDA1 inhibition was obviously weaker than those in the NC group." (PMID 32983961, 2020).
neuroblastoma (7 papers, 2018 to 2025). Neuroblastoma (NB) is the most common solid, extracranial childhood tumor. "Our bioinformatic analyses of multiple datasets available on R2 revealed that the low level of PHLDA1 gene expression associates with the adrenergic, more neuronal-directed state of neuroblastoma." (PMID 38495105, 2024). "Also, in this neuroblastoma model, the downregulation of PHLDA1 caused the increased levels of ERK1/2 in epidermal growth factor (EGF)-treated cells and non-treated cells as well as increased phosphorylation of ERK1/2 in EGF-stimulated cells." (PMID 39630301, 2025). "Notably, PHLDA1 also plays a role in other than neuroblastoma pediatric tumors, e.g., osteosarcoma, where high PHLDA1 expression is associated with a lower overall survival of osteosarcoma patients." (PMID 41430389, 2025). "PHLDA1 silencing decreases the level of secretogranin 2, a marker of neuronal differentiation into sympathetic neurons in neuroblastoma." (PMID 39630301, 2025). "The association between Tollip and PHLDA1 was also made by our group in IMR-32 neuroblastoma cells with PHLDA1 downregulation, as indicated by mass spectrometry." (PMID 39630301, 2025). "Our previous research revealed changes in the proteome of PHLDA1-silenced human neuroblastoma IMR-32 cells." (PMID 41430389, 2025). "Athymic nude mice were injected subcutaneously (s.c.)with shP or shC human neuroblastoma IMR-32 cells to determine the impact of PHLDA1 silencing on xenograft tumor growth and morphology." (PMID 41430389, 2025). "The results showed that silencing PHLDA1 in vivo promoted human neuroblastoma cell survival, decreased the apoptotic potential of the cells, disrupted angiogenesis in developing tumors, and altered collagen network formation." (PMID 41430389, 2025). "The level of ABCB1 following PHLDA1 silencing was assessed in another human neuroblastoma cell line, CHP-134." (PMID 41430389, 2025). "Anti-GD2 ganglioside 14G2a monoclonal antibody (mAb) induced PHLDA1 in IMR-32 neuroblastoma cells, and this event accompanied 14G2a antibody-induced cell death." (PMID 39630301, 2025). "Neuroblastoma tumors with PHLDA1 silencing tended to have greater masses than tumors derived from control cells did." (PMID 41430389, 2025). "In cancer, the lowest level of PHLDA1 protein was found in leukemia-derived cell lines and the highest in neuroblastoma, as shown by analysis of Cancer Cell Line Encyclopedia proteomics dataset of 378 samples from 24 different cancer types." (PMID 39630301, 2025). "In this work, evidence of a more general mechanism of the induction of ABCB1 following PHLDA1 silencing was presented in vitro in two neuroblastoma cell lines, i.e., IMR-32 and CHP-134." (PMID 41430389, 2025). "Our most recent study on the IMR-32 human neuroblastoma cell line revealed noticeable changes in the global proteome and phosphoproteome after PHLDA1 silencing, which led to the upregulation of proteins associated with mitochondria." (PMID 41430389, 2025). "Our in vivo study provided evidence that the silencing of PHLDA1 in neuroblastoma cells significantly influenced tumor growth dynamics, vascularization, and extracellular matrix composition in the applied model." (PMID 41430389, 2025). "Mass spectrometry-based proteomic analyses were applied to better characterize a role of PHLDA1 protein in the response of neuroblastoma cells to chimeric ch14.18/CHO antibody." (PMID 38495105, 2024). "Gene expression profiling showed that PHLDA1 is the most upregulated gene in the studied human neuroblastoma cells." (PMID 38495105, 2024). "Previously performed gene expression profiling helped us to identify the PHLDA1 (pleckstrin homology-like domain family A member 1) gene as the most upregulated gene in the IMR-32 human neuroblastoma cells treated with the mouse 14G2a monoclonal antibody." (PMID 38495105, 2024).
neuroblastoma (continued). "To resolve the biological roles of PHLDA1 in neuroblastoma, we performed quantitative proteomic analysis of PHLDA1-silenced vs. control IMR-32 cells." (PMID 38495105, 2024). "To evaluate the correlation of PHLDA1 expression level with survival of neuroblastoma patients we re-analyzed mRNA microarray results of Tumor Neuroblastoma SEQC dataset from 378 samples, available on R2 platform." (PMID 38495105, 2024). "Taken together, our data indicate that silencing of PHLDA1 sensitizes IMR-32 neuroblastoma cells to EGFR inhibitors treatment." (PMID 38495105, 2024). "We showed that high level of expression of PHLDA1 positively correlates with survival of MYCN-amplified subset of neuroblastoma patients, but proteins regulated by PHLDA1 exhibit both positive and negative correlation with survival of neuroblastoma patients." (PMID 38495105, 2024). "Analysis of Cancer Cell Line Encyclopedia proteomics dataset of 378 samples from 24 different cancer types revealed the lowest level of PHLDA1 protein in leukemia-derived cell lines and the highest in neuroblastoma." (PMID 38495105, 2024). "Previously performed gene expression profiling helped us to identify the PHLDA1 (pleckstrin homology-like domain family A member 1) gene as the most upregulated gene in human IMR-32 neuroblastoma cells treated with the mouse 14G2a monoclonal antibody." (PMID 38495105, 2024). "The analysis revealed that PHLDA1 mRNA level positively correlates with event-free and overall survival of 92 neuroblastoma patients with MYCN-amplification." (PMID 38495105, 2024). "Our results along with findings of other groups prompted us to investigate the possible role of PHLDA1 as an autophagy modulator in neuroblastoma cells." (PMID 30027525, 2018). "Next, we tested how PHLDA1 silencing affects neuroblastoma cells in vivo." (PMID 41430389, 2025). "The increased collagen deposition and collagen net density in shP tumors suggested that PHLDA1 may play a critical role in regulating ECM remodeling in our in vivo neuroblastoma model." (PMID 41430389, 2025). "However, in IMR-32 neuroblastoma cells with downregulated PHLDA1, the expression of autophagy marker LC3A/B-II was increased." (PMID 39630301, 2025). "Finally, our results reveal how PHLDA1 affects molecular pathways in both in vitro and in vivo models and provide insight into its role in human neuroblastoma, which can be beneficial for better understanding the tumor biology." (PMID 41430389, 2025). "Moreover, in IMR-32 neuroblastoma cells, PHLDA1 silencing affected the expression of stem cell markers such as nestin and nanog." (PMID 39630301, 2025). "A more detailed analysis, including co-immunoprecipitation followed by mass spectrometry, indicated that PHLDA1 interacts with DDB1 and CUL4 associated factor 7/autism susceptibility gene 2 protein (DCAF7/AUTS2) complex in neuroblastoma, essential for neuronal differentiation of mouse stem cells." (PMID 39630301, 2025). "Thus, we extended the research to further investigate the role of EGFR and its connotation with PHLDA1 in human neuroblastoma." (PMID 38495105, 2024). "Therefore, our study has shed a new light on functions of PHLDA1 in the neuroblastoma cells, suggesting its role as a pro-apoptotic protein." (PMID 38495105, 2024). "Our previous data indicates that it probably has pro-apoptotic role in IMR-32 cells, but results presented here, with application of anti-GD2 ch14.18/CHO antibodies, indicate that at the same time PHLDA1 might inhibit differentiation of neuroblastoma cells." (PMID 38495105, 2024). "In the present study, cell culture experiments combined with proteomic analyses (mass spectrometry, co-immunoprecipitation, Western blotting) were applied to better characterize a role of PHLDA1 protein in the response of IMR-32 human neuroblastoma cells to chimeric ch14.18/CHO antibody." (PMID 38495105, 2024).
neuroblastoma (continued). "Nevertheless, more data is needed to establish whether PHLDA1 is activated upon anti-GD2 treatment in neuroblastoma patients." (PMID 38495105, 2024). "The mechanism by which PHLDA1 is involved in regulation of neuroblastoma differentiation might relay on its direct interaction with DCAF7/AUTS2 complex, what might lead to alteration in the AUTS2 isoforms balance observed in this study." (PMID 38495105, 2024). "Finally, we explored a role of PHLDA1 protein in regulation of autophagy in CHP-134 neuroblastoma cells." (PMID 30027525, 2018). "Furthermore, we aimed to investigate the response of CHP-134 cells in which PHLDA1 was silenced to doxorubicin to examine whether a similar regulatory effect could be observed in yet another neuroblastoma cell line." (PMID 41430389, 2025). "Furthermore, our bioinformatic analysis indicates that PHLDA1 downregulation might weaken the mesenchymal and enhance adrenergic state of neuroblastoma cells." (PMID 38495105, 2024). "Additionally, downregulation of PHLDA1 caused a significant decrease in the cell cycle inhibitor, CDKN1A (P21) and an increase in expression of TRKB that are among other markers of poor prognosis in neuroblastoma." (PMID 38495105, 2024). "Although, there was no virtual stimulation of autophagy in the 14G2a mAb-treated CHP-134 neuroblastoma cells, we were able to show that PHLDA1 protein positively regulates autophagy and this process exists in a mutually exclusive manner with apoptosis in PHLDA1-silenced CHP-134 cells." (PMID 30027525, 2018). "Our group also showed that in another neuroblastoma cell line, CHP-134, the PHLDA1 protein negatively regulates apoptosis and positively regulates autophagy, showing some differences even between neuroblastoma cell lines." (PMID 39630301, 2025). "Most importantly, the downregulation of PHLDA1 in IMR-32 increased the level of tropomyosin receptor kinase B (TRKB), a marker of poor prognosis in neuroblastoma." (PMID 39630301, 2025). "The significance of PHLDA1 was also observed in ch14.18/CHO and 14G2a monoclonal antibodies response, which are GD2 ganglioside-targeting drugs in neuroblastoma." (PMID 39630301, 2025). "Moreover, PHLDA1 downregulation was shown to affect differentiation-associated transcripts such as ID1, ID2 (encoding inhibitors of differentiation 1, 2), NTRK1, NTRK2 (encoding tropomyosin receptor A, B), and NGF (encoding nerve growth factor) in IMR-32 neuroblastoma cells." (PMID 39630301, 2025). "In conclusion, our results help to elucidate the relationship between PHLDA1 and ABCB1 in human neuroblastoma." (PMID 41430389, 2025). "Further analysis of the regulation between PHLDA1 and efflux pumps (such as ABCB1and ABCC10) is needed in other neuroblastoma cell lines and for treatment with different cytotoxic drugs to establish whether this mechanism operates more broadly." (PMID 41430389, 2025). "The decreased cytotoxicity of doxorubicin was observed following PHLDA1 silencing in the S6 and S17 clones of CHP-134 neuroblastoma cells compared with that in the control cells, and a statistically significant decrease in ATP levels was detected only at the highest concentration tested (150 nM)." (PMID 41430389, 2025). "Similar negative regulation between PHLDA1 and AKT was also reported in IMR-32 neuroblastoma cells." (PMID 39630301, 2025). "Moreover, the level of a marker of poor prognosis in neuroblastoma, TRKB (tropomyosin receptor kinase B), was increased in PHLDA1-silenced cells." (PMID 41430389, 2025). "Therefore, we can conclude that PHLDA1 affected levels of the ABCB1 transporter in IMR-32 and CHP-134 neuroblastoma cells, which impacted on their sensitivity to doxorubicin." (PMID 41430389, 2025). "The downregulation of PHLDA1 also led to a significant increase in the expression of tropomyosin receptor kinase B (TRKB) and aurora A kinase, which are markers of poor prognosis in neuroblastoma." (PMID 39630301, 2025).